ZW10 (zw10 kinetochore protein)
Description:
Essential component of the mitotic checkpoint, which prevents cells from prematurely exiting mitosis. Required for the assembly of the dynein-dynactin and MAD1-MAD2 complexes onto kinetochores. Its function related to the spindle assembly machinery is proposed to depend on its association in the mitotic RZZ complex. Involved in regulation of membrane traffic between the Golgi and the endoplasmic reticulum (ER); the function is proposed to depend on its association in the interphase NRZ complex which is believed to play a role in SNARE assembly at the ER.
Synonyms: KNTC1AP; HZW10
Tractability: Antibody: UniProt places it where antibodies can reach, with high confidence. PROTAC: ubiquitination databases record sites on it; its protein half-life has been measured.
Gene: Protein-coding gene on chromosome 11 (113,733,183 to 113,773,746, reverse strand). Ensembl gene ENSG00000086827.
Subcellular location: Cytoplasm; Endoplasmic reticulum membrane; Chromosome, centromere, kinetochore; Cytoplasm, cytoskeleton, spindle; Lipid droplet
Subcellular location (Human Protein Atlas): Cytosol; Endoplasmic reticulum
Pathways (Reactome):
Cell Cycle: Amplification of signal from unattached kinetochores via a MAD2 inhibitory signal; EML4 and NUDC in mitotic spindle formation; Mitotic Prometaphase; Resolution of Sister Chromatid Cohesion; Separation of Sister Chromatids
Signal Transduction: RHO GTPases Activate Formins
Vesicle-mediated transport: COPI-dependent Golgi-to-ER retrograde traffic
Gene Ontology:
Molecular function: protein binding; centromeric DNA binding
Biological process: endoplasmic reticulum to Golgi vesicle-mediated transport; establishment of mitotic spindle orientation; Golgi organization; mitotic metaphase chromosome alignment; mitotic sister chromatid segregation; mitotic spindle assembly checkpoint signaling; protein localization to kinetochore; protein-containing complex assembly; regulation of exit from mitosis; meiotic cell cycle; regulation of attachment of spindle microtubules to kinetochore; retrograde vesicle-mediated transport, Golgi to endoplasmic reticulum; mitotic cell cycle
Cellular component: cytoplasm; cytosol; Dsl1/NZR complex; endoplasmic reticulum; endoplasmic reticulum membrane; kinetochore; kinetochore microtubule; lipid droplet; membrane; nucleus; RZZ complex; spindle pole; chromosome, centromeric region; spindle
Genetic constraint (gnomAD): Loss-of-function variants: 48 observed, 83.58 expected, observed/expected ratio (o/e) 0.57, 90% interval 0.46 to 0.73. The upper end of that interval is the gene's LOEUF score, 0.73, which puts it in group 2 of 6, group 1 being the genes least tolerant of losing a copy. Missense variants: 798 observed, 926.37 expected, observed/expected ratio (o/e) 0.86, 90% interval 0.81 to 0.91. Synonymous variants: 298 observed, 335.57 expected, observed/expected ratio (o/e) 0.89, 90% interval 0.81 to 0.98.
Homologues: Orthologues: chimpanzee ZW10 (100% identical), macaque ZW10 (99% identical), pig ZW10 (94% identical), dog ZW10 (92% identical), rabbit ZW10 (92% identical), guinea pig ZW10 (88% identical), mouse Zw10 (86% identical), rat Zw10 (85% identical), tropical clawed frog zw10 (71% identical), zebrafish zw10 (60% identical), Drosophila melanogaster Zw10 (21% identical), Caenorhabditis elegans czw-1 (19% identical).
Diseases named in the same sentence as ZW10 in open-access papers:
ZW10 is named in the same sentence as 12 diseases in open-access papers, as found by Europe PMC text mining. Sharing a sentence is not in itself a finding about the gene and the disease. The quoted sentences say what the papers report.
autoimmune conditions (1 paper, 2017). "Novel gene-longevity associations included genes MICA/B (a locus previously linked to autoimmune conditions rheumatoid arthritis and multiple sclerosis), TOX, ZW10, SEMA6D, EGLN2/CYP2A6, EXOC3L2/MARK4 and C20orf187." (PMID 29227965, 2017).
neuroblastoma (1 paper, 2017). Neuroblastoma (NB) is the most common solid, extracranial childhood tumor. "In addition to syntaxin 18, Rab18 interacts with ZW10 kinetochore protein (ZW10) and RAD50 interactor 1 (RINT1), which, together with neuroblastoma amplified gene (NAG), are members of the NRZ complex." (PMID 28815213, 2017).
osteosarcoma (1 paper, 2018). A usually aggressive malignant bone-forming mesenchymal neoplasm, predominantly affecting adolescents and young adults. "Using osteosarcoma cells (U2OS) and normal human dermal fibroblast (HDF), two well-established models for the study of chromosome congression, we demonstrate that miR-155 targets the spindle checkpoint proteins BUB1, CENP-F, and ZW10, thus compromising chromosome alignment at the metaphase plate." (PMID 29560129, 2018).
tumor (2 papers, 2018 to 2024). "Deficiency of PERP has been shown to promote tumor growth, whereas ZW10 is essential in mitotic checkpoint control." (PMID 30071870, 2018). "Our working model suggests that TRPS1 recruits USP4 to stabilize HDAC2 repressing the expression of AES, Casp7, PERP, and ZW10 to confer tumor growth." (PMID 30071870, 2018). "These scenarios fit well with our working model that TRPS1 recruits USP4 to stabilize HDAC2 and represses expression of AES, Casp7, PERP, and ZW10 to confer tumor growth." (PMID 30071870, 2018). "NEK7 expression in four tumour cell lines was significantly down-regulated while ZW10 were upregulated, regardless of protein and mRNA levels." (PMID 38365687, 2024).
infection (1 paper, 2023). The state of being infected such as from the introduction of a foreign agent such as serum, vaccine, antigenic substance or organism. "We found that USE1 and ZW10 expression was significantly increased in infected Calu3 cells at 9 h post-infection compared to the previous time points, and RINT1 had a similar trend." (PMID 36768954, 2023).
ZW10 also shares sentences with these, for which no sentence is quoted: cancer (1 paper); colon cancer (1); congenital heart disease (1); multiple sclerosis (1); rectum cancer (1); rheumatoid arthritis (1); Roberts syndrome (1).